IL1B (interleukin 1 beta)
Diseases named in the same sentence as IL1B in open-access papers (continued):
Sharing a sentence is not in itself a finding about the gene and the disease.
periodontitis (continued). "Besides significant elevation of these biomarkers in the gingivitis and periodontitis groups, our results revealed positive correlation between IL-1β, Pg, and clinical indices (PD and BOP)." (PMID 34001101, 2021). "In addition, the expression of the inflammatory cytokine IL-1β is significantly increased in periodontitis tissues, and an in vitro study demonstrated that IL-1β-treated PDLSCs showed impaired osteogenesis potential." (PMID 33869229, 2021). "LPS stimulation mainly augmented the expression levels of proinflammatory cytokines, including interleukin IL-1 beta (IL1β), tumor necrosis factor-alpha (TNFα), and IL-6, resulting in an inflammatory response and destruction of periodontal tissue during periodontitis." (PMID 34899921, 2021). "As increased P. nigrescens colonization seems to be associated with periodontitis 8, we can speculate that the production of IL-1β in gingival tissue with P. nigrescens infection may play a role in the pathogenesis of periodontitis." (PMID 33390812, 2021). "Similarly, VX765, a caspase-1 inhibitor, reduced the expressions of IL-1β, in PDLCs stimulated with E. coli LPS or P. gingivalis LPS, and decreased the inflammatory responses during periodontitis in vivo." (PMID 35008798, 2021). "Interestingly, our results highlight that the initiation of periodontitis resulted in the increased expression level of IL‐1β protein in the 30 days study period." (PMID 33270996, 2021). "Furthermore, GSDMD, the key executor of pyroptosis, was found to be highly expressed and activated in periodontitis tissues, and we reported for the first time that PDLSCs (CD90+) were the source of IL-1β production in periodontitis patients." (PMID 33869229, 2021). "DC may promote alveolar bone resorption via IL-1β induction in periodontitis patients, but suppress resorption via IL-18 and IL-10 induction in some circumstances." (PMID 34830316, 2021). "It is speculated that IL-1β and IL-8 could be potential therapeutic targets for smoking-related periodontitis." (PMID 34732192, 2021). "To compare PIL landscape-based risk classification with traditional biomarkers for periodontitis, we performed a head-to-head comparison and found that the protein levels of IL-1β, MMP-9, and IL-10 in the PICF do not predict peri-implantitis outcomes." (PMID 34093848, 2021). "For example, a group of researchers has identified the association between the genetic risk factors of biomarkers (IL-1, IL-1β, IL-1α, IL-4, IL-10) and periodontitis in different populations, whereas others found no connection." (PMID 34684209, 2021). "Importantly, increased expression of IL-1β in gingival crevicular fluid correlates significantly with the severity of periodontitis." (PMID 34970269, 2021). "In the oral cavity, higher expression of HMGB1 was detected in gingival tissues and gingival crevicular fluid (GCF) of patients with periodontitis and peri-implantitis, which was accompanied by the elevated concentrations of pro-inflammatory cytokines, such as IL-1β, IL-6, and IL-8." (PMID 34573077, 2021). "IL-1β is a significant cytokine biomarker in the periodontitis development." (PMID 35046930, 2021). "Furthermore, because of IL‐1β's prominence in periodontitis, it has been considered as a potential target for new therapeutics." (PMID 33960130, 2021). "We found that the IL1B -511 T/T genotype was associated to the risk of periodontitis in nonsmokers and in all subjects in this Southern Brazilian population." (PMID 31978095, 2020). "The expression level of Il1β significantly increased 3 days after the periodontitis operation, which reflects the two well-known cytokines that are characteristic of inflammation in periodontitis and are universally used as detection markers in the acute phase of chronic inflammation." (PMID 32523937, 2020). "Interestingly, the ability of IL-1β to discriminate between periodontitis groups decreased when considering GCF levels in deep sites." (PMID 33218047, 2020).
periodontitis (continued). "In gingival fibroblasts, DNMTs are also regulated by inflammatory mediators that play a central role in periodontitis pathogenesis: IL-1β upregulates DNMT1 and downregulates DNMT3a expression, whereas exposure to PGE2 leads to downregulation of both DNMT1 and DNMT3a." (PMID 33256844, 2020). "However, the inflammatory mediators the most involved in periodontitis, IL-1β, IL-6, and TNFα were measured, even partially measured, only in 4 studies." (PMID 32698391, 2020). "IL-1β is an important pro-inflammatory cytokine and participates in periodontitis." (PMID 31900383, 2020). "This review focuses on new cytokine-based strategies related to IL-1β in periodontitis." (PMID 31900383, 2020). "Studies early in 1998 showed that blocking IL-1β resulted in reduced progression of periodontal bone loss and attachment loss in a non-human primate model of periodontitis, suggesting that IL-1 blockage is potentially effective in periodontitis." (PMID 31900383, 2020). "Therefore, IL-1β-mediated increase of gp130 in HGFs will be attractive target for regulation of inflammation cascades in periodontitis lesions." (PMID 31968635, 2020). "It follows that low expression of M1 and M2 in PD patients would be the consequence of local and systemic pro-inflammatory loop lead by IL-6, IL1b and TNFα that down-regulate the macrophage polarization response, reflecting a perturbation in tissue repair in periodontitis." (PMID 32560235, 2020). "Therefore, CatB plays a critical role in regulating innate immune responses in periodontitis by controlling production of IL-1β and TNF-α." (PMID 32328131, 2020). "Interestingly, in this study, it was observed that IL-1β levels were still high in moderate PD sites of highly progressive patients over the 6-month follow-up, although both periodontitis groups had similar GI and BoP scores." (PMID 33218047, 2020). "IL-1β is an essential mediator of the inflammatory response and is involved in cell proliferation, differentiation, and apoptosis, as well as in promoting alveolar bone destruction of periodontitis." (PMID 32604936, 2020). "Also, the cells exposed to H2S secreted higher levels of IL-1β and IL-18 in the periodontitis group compared to the healthy group (p= 0.03 and p= 0.04, respectively)." (PMID 31164964, 2019). "IL-36γ could perpetuate gingival inflammation by increasing pivotal inflammatory cytokines in periodontitis (IL-1β, IL-6 and TNF-α) and alveolar bone resorption through an increase of the RANKL/OPG ratio in OECs." (PMID 31848404, 2019). "Concordantly with these studies performed in vitro, in periodontitis tissue samples, an increase in mRNA of IL-1β, IL-6, IL8, and TNF-α, regulated upon activation normal T cell expressed and secreted (RANTES) and monocyte chemotactic protein-1 (MCP-1), was observed, compared to healthy gingiva." (PMID 31049022, 2019). "Therefore, the regulation of AMTN gene transcription by IL‐1β in gingival epithelial cells is a crucial topic for onset and progression of periodontitis." (PMID 29928577, 2018). "Since then, many studies investigated the relationship between IL-1β polymorphism (rs16944) and chronic periodontitis, with many results that do not coincide and remain debatable." (PMID 30647799, 2018). "In fact, it was suggested that the increased expression of IL-1β in patients with psoriasis might explain why such individuals show more missing teeth and more alveolar bone resorption and periodontitis than healthy individuals, as previously reported." (PMID 29888276, 2018). "Blocking IL-1β resulted in reduced progression of periodontal bone loss and attachment loss in a non-human primate model of periodontitis." (PMID 29986441, 2018). "In a subset of patients with severe periodontitis, locally produced proinflammatory mediators—such as IL-1β, IL-6, and TNF-α—can enter systemic circulation and induce an acute-phase response in the liver that is characterized by an increased level of C-reactive protein (CRP)." (PMID 28243243, 2017).
periodontitis (continued). "However, hypoxia appeared in periodontitis, in which NLRP3, cleaved-caspase-1, interleukin 1 beta (IL-1β) and caspase-1-induced cell death was enhanced in periodontitis specimens." (PMID 29184853, 2017). "In our study, we discovered that local injection of rhIGFBP5 significantly decreased IL-1β expression, indicating that rhIGFBP5 could regulate inflammatory immune responses in periodontitis." (PMID 28962660, 2017). "IL-1β has a fundamental role in the pathogenesis of periodontitis and IL 12 has regulatory effect." (PMID 29299075, 2017). "Because the periodontal status of the donors is unknown, we can only speculate that the cells with higher IL‐1β and IL‐18 responses are from donors more prone to develop periodontal disease." (PMID 29744188, 2017). "Our study verified that NLRP3, cleaved-caspase-1 and IL-1β were enhanced in periodontitis tissues." (PMID 29184853, 2017). "Gingival tissues of chronic periodontitis patients exhibit significantly higher levels of pro-inflammatory cytokines IL-1β, IL-6, IL-8, and TNFα than those of periodontally healthy subjects, hence it is possible that periodontal pathogen OMVs are contributing to this response." (PMID 28890719, 2017). "Here, we hypothesized that the IL1-β levels detected by ELISA in gingival samples might derive from a pre-formed pool because the increase in IL-1β levels after periodontitis challenge precedes the increase in mRNA." (PMID 29249988, 2017). "Moreover, IL-1β is increased in the saliva and gingival sulcus fluid of periodontitis patients and induced bone destruction." (PMID 28962660, 2017). "In addition, salivary levels of IL-1β and MMP-8 are significantly associated with severe periodontitis compared to healthy controls." (PMID 28117682, 2017). "Although pro-inflammatory cytokines such as the interleukin-6 (IL-6) and IL-1β are regarded as osteolytic factors in periodontitis, there are reports suggesting that IL-6 and IL-1β also may drive osteogenic differentiation of PDL cells." (PMID 28597116, 2017). "Therefore, in the present study, the effects of smoking on expression of IL-12 and IL-1β in the gingival tissue of people with chronic periodontitis were evaluated." (PMID 29299075, 2017). "It is, therefore, suggested that elevated gene expressions for IL-1B and TLR2 may constitute a common risk factor for periodontitis and RA." (PMID 25657893, 2015). "In our study, a further interesting finding is the possible involvement of C. pneumoniae in the local chronic inflammation, as suggested by the increased levels of IL-1β and IL-6 detected in the gingival crevicular fluid of the patient with chronic periodontitis." (PMID 26636048, 2015). "Furthermore, IL-1β is used as a biomarker to assess the therapeutic outcomes of patients with chronic periodontitis." (PMID 26078980, 2015). "Salivary IL-1β and IL-6 significantly increased with the severity of periodontitis." (PMID 25884025, 2015). "Another case-control study with Japanese adults demonstrated that the distributions of IL-1B +3954 genotypes and haplotypes of IL-1A +4845 and IL-1B +3954 were unique to patients with RA and periodontitis compared with those with periodontitis and healthy individuals." (PMID 25657893, 2015). "IL-1β is considered to be a critical inducer of the pathogenesis and tissue damage observed in cases of inflammatory bone disorders, including RA and periodontitis, as IL-1β impairs the migration of osteoblasts and upregulates the RANKL expression induced by osteocytes." (PMID 26078980, 2015). "Salivary IL-1β levels increase with the severity of periodontitis." (PMID 25884025, 2015). "Furthermore, the activation of both the NLRP3 and AIM2 inflammasomes is necessary for IL-1β secretion after stimulation with P. gingivalis, the main bacteria that induces periodontitis." (PMID 26078980, 2015). "In this study, baseline salivary IL-1β increased significantly with the severity of periodontitis." (PMID 25884025, 2015).
periodontitis (continued). "There is strong evidence to suggest that salivary IL-1β is a good biomarker of periodontitis in as much as measurement of IL-1β can discriminate periodontitis samples from those provided by healthy volunteers but this finding has not been replicated in all studies." (PMID 24944840, 2014). "Thus, the aim of this study was to investigate in vitro the expression profile of HMGB1 in mouse periodontal ligament fibroblasts (mPDL) stimulated with Escherichia coli LPS or IL-1β, mimicking the inflammatory condition present in periodontitis." (PMID 24692854, 2014). "Another prospective cohort study found that levels of salivary MIP-1α (CCL3) and IL-1β (among 19 other mediators that were assayed) were both significantly elevated in 7 subjects with localised aggressive periodontitis as compared to 41 individuals who stayed healthy." (PMID 24944840, 2014). "Another study evaluated the local effects of RvE1 on periodontitis in rabbits and showed that the anti-inflammatory effects of this bioactive product of omega-3 are due to a reduction in the systemic infla-mmatory markers, C-reactive protein and IL-1β." (PMID 24711890, 2014). "IL-1β is produced by a wide range of periodontal tissues and immune cells and, as such, is considered to have multiple roles in innate and adaptive immune responses to plaque bacteria which feature in the pathogenesis of periodontitis." (PMID 24944840, 2014). "In patients with moderate chronic periodontitis, the immunological homeostasis in relation to neutrophil turnover seems to be sustained, maybe because of IL-1β, which compensates for TNF-α, resulting in limited inflammation." (PMID 25299619, 2014). "In this study their results showed that the levels of IL-1β in the crevicular fluid of patients with periodontitis were higher than those in patients with gingivitis and also that the levels of this interleukin in gingivitis and periodontitis were much higher than in healthy patients." (PMID 24790719, 2014). "There is a well-established association between elevated levels of IL-1β in GCF and periodontitis." (PMID 24944840, 2014). "Further, IL-1β could be seen as a general marker of inflammation but it remains to be determined if it is possible to differentiate between gingivitis and periodontitis." (PMID 23637817, 2013). "Moreover, several studies reported an association between IL-1 polymorphisms and periodontitis as well as CHD; one pattern of IL-1 genetic polymorphisms, characterized by the IL-1α+4845 and IL-1β+3954 markers, is associated with periodontitis." (PMID 23691333, 2013). "As MMP-3 is important for remodeling of inflamed gingival tissues and in periodontal tissue destruction, we used ligature-induced periodontitis and cultured fibroblasts to examine respectively, the roles of PTPα in periodontal tissue destruction and IL-1β signaling leading to MMP-3 expression." (PMID 23940616, 2013). "Furthermore, blockage of IL-1β activity slowed progression of experimental periodontitis in primates." (PMID 22315682, 2012). "Conceptually, this makes p38 inhibitor strategies appealing as a host-modulating agent for treatment of periodontitis because physiologic bone turnover (induced by PTH/PTHrP) would occur, but inflammatory bone loss (induced by LPS, IL-1β, and TNF-α) would be pharmacologically antagonized." (PMID 22315682, 2012). "Some studies reported by these authors establish that patients suffering from severe Periodontitis have an increased local production of inflammatory cytokines (IL-1B, TNF-α and IL-6) and a moderate systemic inflammatory response characterized by raised concentrations of CRP, and other mediators." (PMID 28348657, 2011). "Because IL-1β is produced in the active phase of periodontitis, the aim of this study was to investigate the effects of IL-1β on the formation and the metabolic activity of the biofilm of a periodontal pathogen, A. actinomycetemcomitans, and identify bacterial proteins that interact with IL-1β." (PMID 21533109, 2011).
periodontitis (continued). "Chronic inflammation in rheumatoid arthritis and periodontitis is characterized by increased levels of IL-1β, TNFα and prostaglandin E2 (PGE2), which contribute to destruction of joints and alveolar bone in part through increased production of matrix metalloproteinases (MMPs)." (PMID 17319946, 2007). "Thus, by elucidating the interplay between the identified biomarkers (IL1B, PTGS2, and SELL) and immune cells (Tregs and neutrophils), a more comprehensive comprehension of the potential comorbid mechanisms underlying AAA and periodontitis can be attained." (PMID 40857330, 2025). "In addition, ZBP1 can form a ZBP1-NLRP3 inflammasome complex to mediate caspase-1 activation and IL-1β maturation, suggesting that inflammatory vesicle signalling and PANoptosis may co-exist in the pathological process of periodontitis." (PMID 40612110, 2025). "Future studies should focus on understanding how carriers of these specific HLA-DRB1 alleles may exhibit increased production of pro-inflammatory cytokines, including TNF-α, IL-1β, and IL-6, all of which are central to the tissue destruction seen in periodontitis." (PMID 40283738, 2025). "Therefore, measuring salivary NLRP3 and IL-1β may help identify the presence and severity of chronic or aggressive periodontitis, suggesting potential value for both prevention and treatment." (PMID 41440367, 2025). "Therefore, T2DM may increase NLRP3 expression in patients with chronic periodontitis, with increased IL-1β production." (PMID 41009326, 2025). "The positive correlation between salivary NLRP3 and IL-1β suggests a mutual relationship between these two markers—possibly reflecting their increased presence in periodontal tissues due to the ongoing inflammatory process in periodontitis—and their subsequent detection in saliva." (PMID 40572711, 2025). "IL-1β, a classical pro-inflammatory cytokine associated with periodontal pathology, showed significantly elevated levels in T1DM individuals compared to non-diabetic controls (F = 20.46 and p < 0.0001), particularly in the gingivitis and periodontitis groups (p = 0.03 and p = 0.0001, respectively)." (PMID 41280935, 2025). "However, the GCF total amount of IL-1β was significantly higher in the periodontitis group." (PMID 39964474, 2025). "In addition, a ferroptosis-related ceRNA network has been established in periodontitis research, with seven FRGs like IL1B, hsa-miR-185, hsa-miR-204, hsa-miR-211, and hsa-miR-4306, and 28 lncRNAs found to play an important role in the progression of periodontitis." (PMID 39769377, 2024). "Salivary and plasma levels of IL-1β, IL-6, and TNF-α increase with periodontal disease severity, and plasma MMP-8 and MMP-9 levels decrease after non-surgical periodontal treatment events, supporting the theory of periodontitis causing increased systemic inflammation." (PMID 38672972, 2024). "Considering that inflammatory cytokines such as IL-1β are also elevated in oral chronic inflammatory diseases like periodontitis and that the homeless people have poor oral health and limited opportunities to dental care cytokines concentration may be affected by undiagnosed oral diseases." (PMID 39328992, 2024). "Consequently, IL-1β is a salivary pro-inflammatory cytokine that could potentially indicate current disease activity, severity, and progression for periodontitis and CHD." (PMID 39071510, 2024). "Moreover, this explanation might also interpret the significantly higher level of IL-1β in unstable periodontitis than in stable periodontitis and its accuracy in discriminating these two periodontitis statuses." (PMID 39445112, 2024). "In addition, systemic diseases such as diabetes may enhance NLRP3 expression in patients with chronic periodontitis, with an increase in IL-1β production." (PMID 38817019, 2024).